CYP2D6 (cytochrome P450 family 2 subfamily D member 6 (gene/pseudogene))
Diseases named in the same sentence as CYP2D6 in open-access papers (continued):
Sharing a sentence is not in itself a finding about the gene and the disease.
vivax malaria (continued). "Finally, there are no clinical data analyzed here; a future comprehensive study including such information would provide a better understanding of the implementation of G6PD and CYP2D6 testing on the use of 8-aminoquinolines for vivax malaria elimination." (PMID 36508454, 2022). "Primaquine, a drug of choice for vivax malaria, is metabolized principally via CYP2D6." (PMID 35230160, 2022). "The vivax malaria treatment efficacy is influenced by previous exposure to the parasite (immune status), metabolic impairment (CYP2D6 activity), age (body mass index), partner drug used (that can be either artemisinin-based combination or chloroquine), but also by adherence and bioavailability." (PMID 34998391, 2022). "A total of 34 CYP2D6 genotypes were obtained from blood samples of 320 vivax malaria patients." (PMID 34823523, 2021). "However, Silvino’s study showed that the most common CYP2D6 diploid from vivax malaria recurrence patients were predicted as reduced metabolism *2/*4, indicating that allele *4 would have a negative effect on CYP2D6 enzyme activity." (PMID 34823523, 2021). "Therefore, the risk of G6PD deficiency should be identified prior to receiving anti-relapse treatment of vivax malaria, and that the genotype and enzyme activity of CYP2D6 should be tested as well." (PMID 33743705, 2021). "Since the effectiveness of primaquine (PQ) for the radical cure of vivax malaria is influenced by CYP2D6 activity, we wanted to determine whether the failure of PQ might be linked to CYP2D6 genotypes associated with poor metabolism of PQ." (PMID 34595134, 2021). "In order to understand the specific failure reasons for preventing vivax malaria relapses, a preliminary exploration on the CYP2D6 enzyme activity was carried out in the vivax malaria patients in Yunnan Province population by analysing mutational polymorphism in the coding region of CYP2D6 gene." (PMID 34823523, 2021). "Therefore, the definitive analysis of the role of CYP2D6 status in the success/failure of PART requires that all individuals are at least exposed to vivax malaria." (PMID 30999967, 2019). "CYP2D6 status was not the dominant factor for PART failure causing relapsing vivax malaria in a cohort of ADF personnel returning from deployment in PNG and East Timor between 1999 and 2001." (PMID 30999967, 2019). "A more comprehensive understanding of CYP2D6 variation will help us better understand and ultimately predict interindividual PQ response, especially in the Malagasy and other admixed populations, where vivax malaria is a complex clinical and public health problem." (PMID 35230160, 2022). "Eight mutant allelic types were found only in the SR group, yet the association between these different CYP2D6 genotypes and the relapse of vivax malaria could not be established." (PMID 33743705, 2021). "Firstly, the sample size of suspected recurrence of vivax malaria is not large enough, and the alleles (*4, *m-*x,) of CYP2D6 genes with low frequency of distribution might not be quantitatively analyzed." (PMID 33743705, 2021). "However, the impaired degree of CYP2D6 enzyme activity induced by non-functional star allele *3, homozygous diploid *3/*3, as well as the dose–effect relationship between the copy number and the relapses occurring vivax malaria patients remains to be clarified." (PMID 34823523, 2021).
Anxiety (21 papers, 2016 to 2025). Intense feelings of nervousness, tension, or panic often arise in response to interpersonal stresses. "Behavioral characteristics like anxiety and impulsivity have been related to CYP2D6 polymorphisms and their relationship with serotonin/dopamine balance, drug–drug interaction, efficacy, and adverse effects in psychotic disorders treatments." (PMID 40126262, 2025). "The top two ADRs associated with SSRIs metabolized by CYP2D6 are: nightmare (n = 983) reporting odds-ratio (OR) = 4.37 (95% confidence interval (CI) [3.67–5.20]) and panic attack (n = 1,243) OR = 2.43 (95% CI [2.11–2.79])." (PMID 31616600, 2019). "CYP2D6 ultrarapid metabolizers have shown increased use of medications for nausea, anxiety, and hot flashes, along with higher early discontinuation rates (HR: 2.06, 95% CI: 1.11, 3.82)." (PMID 40369345, 2025). "Lower CYP2D6 activity scores were also associated with a higher overall 5D-ASC score and particularly more “Anxious Ego Dissolution,” which includes “Anxiety” and “Impaired Control and Cognition”." (PMID 39231959, 2024). "The CYP2D6 activity score was also negatively associated with the 5D-ASC total score and, in particular, with “Anxious Ego Dissolution,which includes “Anxiety” and “Impaired Control and Cognition”." (PMID 39231959, 2024). "Patients with higher values of the duloxetine metabolic index (DMI) for CYP2D6, indicating a faster metabolism, achieved a greater reduction in anxiety symptoms." (PMID 37686266, 2023). "In terms of the reduction in anxiety symptoms, we found a significant impact of two factors: the CYP2D6 DMI and UKU-SERS." (PMID 37686266, 2023). "Patients with a slow metabolism of duloxetine in relation to the CYP2D6 experienced a lower reduction in anxiety symptoms." (PMID 37686266, 2023). "Specifically, the present study aimed to assess the influence of the CYP2D6 and CYP1A2 gene polymorphisms on the effectiveness of duloxetine in reducing depressive and anxiety symptoms among patients with MDD." (PMID 37686266, 2023). "This study aimed to investigate the influence of the CYP2D6 and CYP1A2 gene polymorphisms on the efficacy of duloxetine in reducing depressive and anxiety symptoms." (PMID 37686266, 2023). "The aim of this study was to assess the influence of the CYP2D6 and CYP1A2 gene polymorphisms on the efficacy of duloxetine treatment in reducing depressive and anxiety symptoms among patients with MDD." (PMID 37686266, 2023). "Although all variants improved with treatment, only CYP2D6-NM and IM showed significant differences as compared with basal HDRS score values, following a similar yet more modest pattern to that observed for anxiety." (PMID 33920985, 2021). "Antidepressant usage/dosage modification, and maternal depression and anxiety, according to CYP2D6 predicted phenotype." (PMID 28769788, 2017). "For example, a long allele is associated with a better response to citalopram, paroxetine, fluoxetine, risperidone, and clozapine, while CYP2D6 and CYP2C19 variants are associated with antidepressant-induced symptoms, such as nightmares, anxiety, and panic attacks." (PMID 38002991, 2023). "The higher abundance of 5-HT and 5-hydroxyindole acetic acid in brain was found in human CYP2D6-transgenic mice than wild-type mice and the transgenic mice were more able to adapt to anxiety, providing direct evidence that brain CYP2D6 catalyzes 5-HT formation from 5-MT." (PMID 33967789, 2021). "Specifically, ratings on the 5D-ASC total, AED subscale (including disembodiment, impaired control and cognition, and anxiety), and VR subscale (including complex and elementary imagery and changed meaning of percepts) significantly increased in PMs compared with functional CYP2D6 subjects." (PMID 34035391, 2021). "Patients with higher values of the CYP2D6 DMI, indicating faster metabolism of duloxetine, achieved a greater reduction in anxiety symptoms as a result of the treatment." (PMID 37686266, 2023).
Anxiety (continued). "In summary, the results of our study indicate a significant influence of CYP2D6 metabolism on the reduction in anxiety symptoms, without a distinct impact on the reduction in depressive symptoms." (PMID 37686266, 2023). "CYP2D6 PMs mainly had greater LSD-induced ratings of AED and VR but not OB, and these subjects may have an overall more challenging acute experience, with higher acute anxiety and possibly even lower therapeutic effects." (PMID 34035391, 2021). "Moreover, it has been observed that individuals with an absent or defective CYP2D6 gene who express a poor metabolizer phenotype are more associable and anxiety-prone, which may be ascribed to a low serotonin level in the brain limbic system." (PMID 37233670, 2023).
Parkinson disease (18 papers, 2012 to 2026). A progressive degenerative disorder of the central nervous system characterized by loss of dopamine producing neurons in the substantia nigra and the presence of Lewy bodies in the substantia nigra and locus coeruleus. "Other contributing factors of Lewy-type pathology include male gender, having late-onset Parkinson’s disease (PD), and carrying the CYP2D6*4 allele and specific alpha-synuclein haplotypes such as L478 and Rep1, among others." (PMID 37629187, 2023). "For example, CYP2D6 is known to decrease its activity in the context of pesticide exposure, raising the risk of neurotoxicity and Parkinson’s disease." (PMID 37368581, 2023). "Lu demonstrated that the poor metabolizer phenotype of CYP2D6 confers a significant genetic susceptibility to Parkinson’s disease in Caucasians." (PMID 29422030, 2018). "Meanwhile, CYP2D6 with decreased activity is implicated in Parkinson disease in Caucasian populations." (PMID 27329697, 2016). "Similarly, polymorphisms in CYP2D6 have been implicated in pesticide metabolism and linked to increased risk for Parkinson's disease and pesticide-induced neurotoxicity among occupationally exposed populations." (PMID 41158796, 2025). "Genetic defects in CYP2D6 have been associated with Parkinson's disease, which may be linked to the role of CYP2D6 in dopamine metabolism in the brain." (PMID 22482072, 2012). "Furthermore, lower levels of CYP2D6 in the brain have been associated with Parkinson’s disease." (PMID 36623884, 2023). "Therefore, future studies should analyze the possible interaction between CYP2D6 gene variants and the variants of the SLC6A3, HTR2C and HTR6 genes on the risk for haloperidol-induced parkinsonism." (PMID 36551993, 2022). "DNM1L is also closely related to the metabolism of exogenous substances and drug metabolism of cytochrome P450 (CYP450), and mitochondria-targeted cytochrome P450 2D6 (CYP2D6) can efficiently catalyze the MPTP compounds that may induce Parkinson’s disease in humans." (PMID 39507763, 2024).
lung carcinoma (12 papers, 2003 to 2024). "By a meta-analysis, a minor but statistically significant association of CYP2D6 polymorphism with lung cancer susceptibility was established." (PMID 33192522, 2020). "Variations in the CYP2D6 genotype-phenotype have previously been reported in patients with lung cancer." (PMID 38668482, 2024). "In lung cancer patients, CYP2D6 genotype–phenotype mismatches had already been reported more than 25 years ago." (PMID 32906709, 2020). "A549 human lung cancer cell line was used as positive control which shows prominent CYP2D6 protein expression." (PMID 24886861, 2014). "That is, the smoking-gene interaction means that some smokers are at greater risk of developing lung cancer, with several host characteristics (i.e., K-ras, GSTM1, CYP2D6, c-MET, NKX2-1, LKB1, BRAF) implicated in lung cancer onset." (PMID 20843376, 2010). "More recently, an association with a protective effect against papillary thyroid cancer has been found with the homozygous mutant CYP2D6 genotype and similar results have been reported for tumors at other sites, such as lung cancer and leukaemia." (PMID 18423013, 2008).
psychosis (12 papers, 2021 to 2025). "This study aims to explore the associations between CYP2D6 pharmacogenetic profiles, baseline neuroimaging findings, and clinical outcomes in children and adolescents diagnosed with psychotic disorders." (PMID 40863997, 2025). "This study investigated the relationship between CYP2D6 genetic polymorphisms, baseline neuroimaging findings, and clinical outcomes in a cohort of children and adolescents with psychotic disorders." (PMID 40863997, 2025). "Currently, only psychosis drugs with PGx associations for the CYP2D6 gene have been assigned the highest level of evidence (LoE) and have clinical dosing guidance." (PMID 38494658, 2024). "This will be the first study of its kind to explore the prescribing of psychosis drugs with CYP2D6 PGx associations in a UK EIP cohort." (PMID 38494658, 2024). "Research on the pharmacogenetic influence of hepatic CYP450 enzyme 2D6 (CYP2D6) on metabolism of drugs for psychosis and associated outcome has been inconclusive." (PMID 39344086, 2024). "Pharmacogenomic (PGx) testing can help clinicians tailor the choice or dose of psychosis drugs to an individual’s genetics, particularly psychosis drugs with known variable response due to CYP2D6 gene variants (‘CYP2D6-PGx antipsychotics’)." (PMID 38494658, 2024). "This study aimed to investigate the relationship between the CYP2D6 polymorphism and optimal clinical results in adolescents with psychosis." (PMID 38540107, 2024). "The proportion of prescribing psychosis drugs with CYP2D6 PGx associations and whether any groups are more likely to be prescribed one." (PMID 38494658, 2024). "Among the 170 propsychotic target genes, 8 were a high-confidence psychosis risk gene (GRIN2A, DRD2, CYP2D6, CHRNB4, CHRM4, GABBR1, GRM3, CHRNA3)." (PMID 40701976, 2025). "This study demonstrates that combining CYP2D6 pharmacogenetic profiling with neuroimaging biomarkers enhances the precision of antipsychotic treatment in children and adolescents with psychotic disorders." (PMID 40863997, 2025). "The results indicate a notable interindividual variability in CYP2D6 enzyme activity among pediatric patients with psychotic disorders." (PMID 40863997, 2025). "In this study, pharmacogenetic profiling was conducted to identify the CYP2D6 metabolizer status of patients diagnosed with psychotic disorders." (PMID 40863997, 2025). "This study has for the first time demonstrated high rates of prescribing drugs for psychosis with dosing recommendations based on CYP2D6 genotype in an EIP cohort, yet adoption of PGx testing to determine CYP2D6 genotype is to date limited." (PMID 38494658, 2024). "Here we evaluate the impact and predictive value of CYP2D6 phenoconversion in patients with psychotic disorders under pharmacological treatment." (PMID 39310932, 2024). "The impact of performing CYP2D6 PGx testing on psychosis clinical outcomes should also be investigated." (PMID 38494658, 2024). "Only psychosis drugs assigned a LoE = Level-1A for dosing guidance based on CYP2D6 genotype were included in the ‘CYP2D6-PGx’ group." (PMID 38494658, 2024). "In the smaller group containing only the four most common drugs for psychosis, 80 patients reported using one or more CYP2D6 inhibitor(s), leading to 51 cases of phenoconversion (78.4% male, mean age 27.8 ± 7.4)." (PMID 39310932, 2024). "Of these PM patients (n = 17), half were taking a primary medication for psychosis metabolized by CYP2D6 (risperidone: n = 5; haloperidol: n = 1; aripiprazole: n = 3)." (PMID 39344086, 2024). "The type of transition was grouped, based on the CYP2D6-PGx status of the initial and new drug for psychosis." (PMID 38494658, 2024). "Patients who were prescribed at least one treatment drug for psychosis at measurement 1 (baseline) and for whom genotype-predicted phenotype of CYP2D6 was available were selected." (PMID 39344086, 2024).
psychosis (continued). "This study is the first to highlight high rates of prescribing drugs for psychosis with clinical recommendations based on the CYP2D6 genotype in EIP services, yet PGx testing to determine the CYP2D6 genotype is not available in EIP settings." (PMID 38494658, 2024). "It has shown that many psychosis drug transitions involve a ‘CYP2D6-PGx antipsychotic’ and some transitions were directly between these psychosis drugs." (PMID 38494658, 2024). "Currently prescribed drug for psychosis – ‘CYP2D6-PGx antipsychotic’ versus ‘non-CYP2D6 antipsychotic’." (PMID 38494658, 2024). "For drugs prescribed in psychosis, the CYP2D6 enzyme has been described as the most important metabolizing gene." (PMID 39344086, 2024). "Here, we show a high frequency of CYP2D6 UMs among subjects with a psychotic disorder throughout the country." (PMID 35197553, 2022). "This study aimed to investigate whether integrating CYP2D6 pharmacogenetic profiles with structural neuroimaging findings can enhance personalized treatment and predict clinical outcomes in pediatric psychotic disorders." (PMID 40863997, 2025). "Several groups, including the Dutch Pharmacogenetic Working Group (DPWG) and the Clinical Pharmacogenetics Implementation Consortium, have formulated pharmacogenetic dosing guidelines, including for drugs for psychosis and depression, and (among other pharmacogenes) CYP2D6." (PMID 39310932, 2024). "PGx testing is a reliable method to determine the CYP2D6 genotype, which can be used to guide psychosis drug prescribing and may improve treatment outcomes." (PMID 38494658, 2024). "CYP2D6 genotype can predict plasma drug levels and clinical outcomes for some psychosis drugs." (PMID 38494658, 2024). "Patients were eligible for inclusion if they were already diagnosed with a non-affective psychotic disorder, and were genotyped a posteriori, during the “Genetic Risk and Outcome of Psychosis” (GROUP) study for which CYP2D6 phenotype was not a main outcome." (PMID 39344086, 2024). "There is evidence that variation in the CYP2D6 genotype, leading to non-normal metaboliser status, causes clinically relevant differences in plasma levels of specific psychosis drugs." (PMID 38494658, 2024). "Most psychosis drug transitions (80%) in this cohort involved a ‘CYP2D6-PGx antipsychotic’." (PMID 38494658, 2024). "Of those prescribed a ‘CYP2D6-PGx antipsychotic’, it was observed that 75 (31%) patients had two or more transitions and that of these patients 56 (23%) would have met the criteria to offer a PGx test, based on current guidance, following the first two psychosis drug trials." (PMID 38494658, 2024). "In summary, the optimization of CYP2D6 and CYP2C19 genotyping is relevant for the implementation in cases as severe and clinically important as suicide or psychosis." (PMID 39598523, 2024). "The study only explored one route of psychosis drug metabolism using CYP2D6, and despite it playing a major role in metabolism, other cytochrome P450 enzymes, such as CYP1A2, CYP2C9/19 or CYP3A4/5 offer alternate metabolism routes for psychosis drugs." (PMID 38494658, 2024). "Not all psychosis treatment drugs would be affected by phenoconversion of CYP2D6, as there are differences in metabolic pathways and involvement of CYP2D6." (PMID 39310932, 2024). "This study demonstrated high rates of prescribing ‘CYP2D6-PGx-antipsychotics’ in an EIP cohort, providing a rationale for further exploration of how PGx testing can be implemented in EIP services to personalise the prescribing of drugs for psychosis." (PMID 38494658, 2024). "Although other medication may thus not be affected by individual variance in CYP2D6 metabolization, this enzyme remains the strongest candidate for PGx-guided treatment for psychopharmaceutics and psychosis medication." (PMID 39344086, 2024). "Not all drugs intended to treat psychosis are metabolized through CYP2D6, however." (PMID 39344086, 2024).
psychosis (continued). "CYP2D6 phenotype may only have a limited or specific effect in treatment using drugs for psychosis and does not appear to affect medication choice or dose in practice for most patients." (PMID 39344086, 2024). "In addition to replicating and expanding on existing work, this study may further contribute to the field of PGx by investigating a potential hypothesis contributing to the lack of conclusive results in PGx studies examining CYP2D6 and treatment outcomes of drugs for psychosis." (PMID 39344086, 2024).